AFP (alpha fetoprotein)
Diseases named in the same sentence as AFP in open-access papers (continued):
Sharing a sentence is not in itself a finding about the gene and the disease.
tumor (continued). "The tumour markers showed AFP (alpha-fetoprotein) of 1.48 ng/mL, CEA (carcinoembryonic antigen) of 41.98 ng/mL, and CA125 and CA199 were not significantly abnormal." (PMID 38919528, 2024). "AFP and β-hCG serve as useful tumor markers for iGCTs, despite ongoing debates about optimal cutoff values." (PMID 38835384, 2024). "Low circ_003570 was positively associated with a larger tumor size (>5 cm), vessel invasion, an advanced HCC stage, and a higher AFP serum level." (PMID 39596302, 2024). "HCC-specific tumor markers like alpha-fetoprotein (AFP) and des-gamma (γ)-carboxy prothrombin (DCP) offer advantages in their simplicity, speed, and objective, and are broadly utilized in HCC screening, diagnosis, and risk stratification." (PMID 38903723, 2024). "CT and MRI are used to evaluate the size and characteristics of the residual mass and tumour markers, such as alpha-fetoprotein (AFP), human chorionic gonadotropin (HCG) and lactate dehydrogenase (LDH), to determine the response to therapy and relapse." (PMID 39001474, 2024). "Among the nomogram predictors, size had the highest score (100 points on the scale axis), followed by AFP, tumour margin and APE (30 points, 18 points and 16 points, respectively)." (PMID 38281008, 2024). "Stratified analyses by tumor size (<50 mm vs. ≥50 mm), AFP levels (<200 ng/mL vs. ≥200 ng/mL), and TBIL levels (<20 μmol/L vs. ≥20 μmol/L) yielded similar findings, with HRs exceeding 2 in all strata." (PMID 39902133, 2024). "In the multivariate analysis, we noted that PNS was strongly associated with the AFP value and an HCC size of over 2 and 5 cm and with the BCLC class, indicating a correlation with tumor activity." (PMID 38674198, 2024). "The univariable regression analysis revealed that TBS, age, HBV-DNA, tumor diameter, number of tumors, preoperative AFP level, liver margin status, MVI, and BCLC staging were significantly correlated with RFS (P < 0.05)." (PMID 39555448, 2024). "AFP levels before LT, the number and size of nodules, poor differentiation of the tumor, and the presence of microvascular invasion (mVI) or satellitosis on explant are strongly associated with the risk of HCC recurrence." (PMID 39272917, 2024). "Tumor markers including serum alpha-fetoprotein (AFP) and beta subunit of human chorionic gonadotropin (β-HCG) as well as routine blood investigations were all within normal limits." (PMID 39544589, 2024). "Preoperative tumor markers (α fetoprotein [AFP], β human chorionic gonadotropin [b hCG], and lactate dehydrogenase [LDH]) were investigated at baseline and were followed postoperatively if they were elevated." (PMID 39686951, 2024). "Except for MVI, all remaining parameters (Serum AFP levels, number of tumors, and largest tumor size) of RETREAT score can be assessed during the pre-transplant phase, therefore predicting MVI before liver transplantation for better patient selection." (PMID 39749089, 2024). "Subgroup analysis showed that for patients with a maximum tumor diameter greater than 7 cm, AFP > 400 ng/ml and accompanied by portal vein tumor thrombus, and Child-Pugh class A, there was a statistically significant difference in OS between TLT and TL groups." (PMID 39411718, 2024). "Among the patients from hospital A, 19% (n=50) had a high tumor load (tumor size >100mm), 45.9% (n=137) had more than one lesion, 27.4% (n=72) had bilobular invasion, and 23.2% (n=61) exhibited an elevated AFP level (>400 ng/mL)." (PMID 39258671, 2024). "Almost all YST patients exhibit elevated AFP levels in serum and cerebrospinal fluid, likely due to tumor cells retaining the ability to synthesize AFP, as seen in embryonic yolk sac." (PMID 39711964, 2024). "Subsequently, the genomic hallmarks such as CNA and FS were measured based on shallow whole genome sequencing, and the protein tumor marker AFP was quantified by the Roche Cobas e411." (PMID 39704423, 2024).
tumor (continued). "Univariate analysis found that tumor shape, vascular type, necrosis, AFP and LR-M were statistically different between the MVI-positive group and MVI-negative group." (PMID 39546065, 2024). "Known risk factors for early relapse include male gender, large tumor size, tumor multifocality, high serum alpha-fetoprotein level and many others." (PMID 39330022, 2024). "Early recurrence commonly interacts with tumor-related factors such as AFP, tumor number, tumor size, poor differentiation, and vascular invasion." (PMID 38612974, 2024). "Subsequently, we further explored the robustness of our ML predictive model through subgroup analysis by stratifying patients based on preoperation AFP levels, tumor size, and tumor number." (PMID 39440446, 2024). "To date, the clinical blood tumor biomarkers are limited, including alpha-fetoprotein (AFP), cancer antigen 19-9 (CA19-9), and carcinoembryonic antigen (CEA), all of which demonstrate low sensitivity." (PMID 39735533, 2024). "The independent factors (TIGIT expression, AFP level, and tumor size) determined by multivariate analysis to impact postoperative OS were incorporated into the calculation of the concordance index." (PMID 39540362, 2024). "In clinical practice, AFP is used as a tumor and gestational marker; however, more and more research studies have indicated a relationship between AFP levels and ovarian masses." (PMID 38379864, 2024). "Univariate analysis revealed that the clinical factors tumour size and serum AFP level and the imaging features tumour margins and APE were significantly correlated with MVI (p < 0.05) in all three datasets." (PMID 38281008, 2024). "The serum tumor markers beta-human chorionic gonadotropin (β-hCG), alpha-fetoprotein (AFP), and lactate dehydrogenase (LDH) are clinical standards for GCT diagnosis and follow-up194." (PMID 39097671, 2024). "have made the candidate selection more reasonable by incorporating tumor biological biomarker α‐fetoprotein (AFP) and pathological classification." (PMID 39188937, 2024). "Similar findings were found in reference to the tumor markers AFP (71%, N = 17/24) and PIVKA II (66.6%, N = 10/15)." (PMID 39272934, 2024). "Compared to tumor size and AFP, two traditional prognostic markers in HCC, H‐IME score showed larger area under curve (0.8079 in cohort C2, 0.8540 in cohort C3), indicating a better predictive ability." (PMID 39659057, 2024). "AFP-targeted CAR-T cells have demonstrated the capability to significantly inhibit tumor growth both in vivo and vitro." (PMID 39569202, 2024). "These LT criteria for HCC mainly consider tumour-related factors, such as tumour morphological characteristics and alpha-fetoprotein (AFP) levels." (PMID 38461206, 2024). "The conclusion revolves around the correlation between AFP positivity and adverse prognosis, tumor progression and metastasis, premature death, and other outcomes." (PMID 38438972, 2024). "The results showed that LDHD gene expression was significantly associated with age, gender, race, T stage, histological grade, pathological stage, tumor status and AFP." (PMID 38291366, 2024). "Tumor markers like serum Alpha-fetoprotein (AFP), Carcinoembryonic antigen (CEA), total Human Chorionic Gonadotropin (HCG), and Carbohydrate antigen (CA) 19.9 were within normal limits." (PMID 39845895, 2024). "Univariate analysis revealed that rs16944 A/A genotype (p < .01), alpha‐fetoprotein (AFP) level (p < .01), des‐gamma‐carboxyprothrombin (DCP) level (p = .03), tumor size (p < .01), and number of CTCs were associated with mPVI." (PMID 38798075, 2024). "The expression of TKT was significantly correlated with tumor size and Edmondson grade, and AFP (P<0.01)." (PMID 38434975, 2024). "Tumor markers (AFP 1.75ng/ml, CEA 0.73 ng/ml, CA199 4.16U/mL, CA125 13.20U/mL, HE4 26.35pmol/L, HCG<1.20mIU/mL), thyroid function, insulin release test and adrenal function were within normal ranges." (PMID 39026973, 2024).
tumor (continued). "The RETREAT score, which is calculated based on the AFP levels at transplantation, mVI, and the largest viable tumor on explant, has been extensively validated." (PMID 39272917, 2024). "Recently proposed pre-LT selection criteria have evolved to encompass markers of tumor biology, such as alpha-fetoprotein (AFP) and responsiveness to locoregional treatments." (PMID 38835378, 2024). "Abnormally expressed alpha-fetoprotein (AFP) in HCC has an inhibitory effect on tumor immune surveillance." (PMID 37609076, 2023). "To explore the clinical implications of RR subunits, we compared the differences of RRM1, RRM2, and RRM2B among clinicopathologic features, including age, race, gender, T stage, grade, stage, tumor status, and alpha-fetoprotein (AFP) level." (PMID 36713030, 2023). "Strictly before the start of treatment, saliva samples were obtained and the concentrations of tumor markers (AFP, NSE, HE4, CA15-3, CA72-4, CA125 and CEA) were determined using an enzyme immunoassay (ELISA)." (PMID 37367072, 2023). "This relates to our recent analysis of the impact of the immune-suppressive tumor-derived alpha fetoprotein (AFP) on DC function." (PMID 37938561, 2023). "Univariate analysis of OS identified 12 variables as prognostic factors: AFP, tumor size, tumor number, Edmondson grade, tumor capsule, MVI, PVTT, BCLC stage, VCE, Ki67, M-CTC and the combination of M-CTC and Ki67." (PMID 36600214, 2023). "Tumor size, tumor number, AST, and ALT levels were all encoded as continuous data, but AFP levels were encoded as categorical data (AFP <400 ng/mL vs. ≥400 ng/mL)." (PMID 37200967, 2023). "Nevertheless, other factors can affect the levels of AFP, including the cancer stage and tumor size, and as such, this technique lacks sufficient specificity and sensitivity to effectively diagnose HCC." (PMID 38022557, 2023). "The combination of AFP serum assay and ultrasound significantly increases the sensitivity of tumor detection." (PMID 36831565, 2023). "In the development cohort, univariate analysis revealed that total CTC counts, AFP, tumor size, Edmondson grade, node number, tumor capsule, KI67, and MVI/PVTT status were significantly associated with EHR after hepatectomy (all p < 0.05)." (PMID 37337754, 2023). "Catalase and GSH, with significantly increased MDA levels, subsequently increased the tumor biomarkers (AFP and CEA)." (PMID 36850982, 2023). "Second, AFP was the only tumor marker for HCC included in the study, and AFP-L3 or PIVKA-II levels were unavailable in the study population." (PMID 37565915, 2023). "In summary, the present data demonstrate that combining AFP immunization with anti-PD1 administration increases AFP499+ CTLs in tumor lesions, leading to delayed HCC progression." (PMID 37040183, 2023). "Serum α‐fetoprotein (AFP) is a typical tumor biomarker of HCC and plays a crucial function in monitoring, diagnosing, and determining the prognosis of HCC patients." (PMID 38130028, 2023). "Those patients diagnosed above 8 years old, presented with distant tumor stage and AFP remained ≥106 ng/mL after NAC had worse survival outcomes (p<0.01)." (PMID 37124543, 2023). "The survival rates and disease-free survival rates are influenced by factors such as AFP value, total tumor number, and total tumor diameter." (PMID 37909200, 2023). "The valuable clues in the diagnosis of S-HCC preoperatively also included: patients with HBV infection, elevated AFP level, large tumor size, irregular and unclear tumor margin, intrahepatic metastasis and hepatic surface retraction." (PMID 37428205, 2023). "Third, the risk scoring formula consisted of three independent prognostic factors (AFP, tumor size and albumin), but their interaction effects were ignored." (PMID 37434986, 2023). "Whereas AFP levels reflect intrahepatic tumour burden, PIVKA-II levels reflect tumour behaviour such as vascular invasion and extrahepatic disease." (PMID 37780370, 2023).
tumor (continued). "High risk HB criteria include patients with preoperative PRETEXT IV, serum AFP < 100 ng/ml, distant metastasis at diagnosis, invasion of the portal vein, inferior vena cava or hepatic vein and tumor rupture or intraperitoneal hemorrhage." (PMID 37124183, 2023). "In conclusion, the anti-inflammatory, proapoptotic, anticarcinogenic effects of EA on HCC were evident by declining hepatic injury markers, ALT, AST, and ALP, tumor biomarkers, AFP and GGT, and restoration of the distorted hepatic structure." (PMID 37835585, 2023). "We developed a simple-to-implement RESected Tumor Outcome and Recurrence (RESTORE) index comprising three commonly assessed variables: alpha-fetoprotein level, vascular invasion, and tumor burden." (PMID 37173900, 2023). "We extracted clinicopathological data of LIHC patients from the TCGA database, encompassing variables such as age, gender, tumor stage, grade, vascular invasion, residual tumor status, hepatic inflammation, and AFP levels." (PMID 37817774, 2023). "Clinical data analysis indicated that low expression of FCN3 was significantly correlated with AFP, tumor size, number of tumors, microvascular invasion and Edmondson-Steiner classification in 202 patients of HCC." (PMID 36632465, 2023). "Because increased AFP levels are related to the microvascular invasion of HCC, in 2012, a French retrospective multicenter analysis designed a model that added AFP to tumor burden." (PMID 38137868, 2023). "For example, M0 macrophages can be polarized into immunosuppressive M2 macrophages upon stimulation with tumor-derived alpha fetoprotein and inhibit M1 macrophages from phagocytosing HCC cells." (PMID 37662906, 2023). "The frequency of complete tumor necrosis was higher in the CR group; however, the AFP and pathologic response groups had only borderline significance." (PMID 36900345, 2023). "AFP has also been proved to promote tumor cell proliferation and inhibit cell apoptosis, and has an important relationship with the occurrence and development of HCC." (PMID 37920165, 2023). "Given their ability to stimulate the CTL response, DCs are currently studied for vaccine therapy using specific tumour antigens such as AFP, GPC-3 and MAGEA-1, or total lysate-pulsed." (PMID 37509293, 2023). "By multivariate analysis, we identified naïve/recurrence, number of nodules, size of the largest tumor, total bilirubin, albumin and AFP levels as independent predictors of overall survival in intermediate stage HCC patients." (PMID 38007597, 2023). "Serum alpha-fetoprotein (AFP) has been commonly used as a tumour biomarker for the detection of HCC and to monitor the course of the disease." (PMID 37024609, 2023). "Univariable and multivariable analyses revealed that treatment type, Child–Pugh class, pretreatment AFP level, and tumor size were significantly predictive of prognosis." (PMID 37370774, 2023). "In subgroup analyses, the similar results were observed in patients with following tumor characteristics: Maximum diameter plus number of viable tumor ≥ 5, with MIV or MAT, AFP at LT ≥ 20 ng/ml, and well or moderate tumor grade." (PMID 36650583, 2023). "Metastatic recurrence of NGGCTs is often accompanied by the elevation of tumor markers AFP and/or β-HCG, but in this case, continuous monitoring of serum markers after treatment was always negative." (PMID 37679697, 2023). "The correlation analysis revealed that high-risk score was associated with increased tumor grade (P = 0.002), TNM stage (P = 0.002), Serum AFP level (P = 0.021), higher recurrence rate (P < 0.001), and lower alive rate (P < 0.001)." (PMID 37014321, 2023). "The linear model for RMST differences showed factors associated with better OS at 1 year included younger age, lower AFP level, lower PT, solitary tumor, presence of tumor encapsulation, smaller tumor, and better than grade 2 MVI (eTable 2 in Supplement 1)." (PMID 37906195, 2023).
tumor (continued). "Among the tumor markers alpha fetoprotein (AFP), carcinoembryonic antigen (CEA), and carbohydrate antigen 19-9 (CA19-9), the level of CEA was significantly associated with CRC metastasis." (PMID 37362927, 2023). "While Alpha fetoprotein (AFP), a key marker of tumour burden and prognosis, was assessed using ELISA." (PMID 36874031, 2023). "In the present study, AFP, tumor size and albumin were identified as independent prognostic factors, which was consistent with previous studies and indicated high heterogeneity in such patients." (PMID 37434986, 2023). "We found that ctDNA is a good surrogate marker of tumor burden and have confirmed the capacity of serial ctDNA sampling to monitor dynamic tumor response, similarly to AFP." (PMID 38201440, 2023). "Several studies have established a correlation between CTC positivity and/or count with various aspects related to HCC, such as tumor size, portal vein tumor thrombus, AFP levels, degree of differentiation, and disease stage." (PMID 37445822, 2023). "The dual properties of AFP provide the possibility of future personalized chemotherapy (tumor destruction) and immunotherapy (reduced tolerance)." (PMID 36768863, 2023). "Given the importance of tumor microenvironments for both tumorigenesis and immunogenicity, we analyzed differential expression of CmPn network genes, along with AFP, among immune subtypes for both HCCs and CCAs." (PMID 36980321, 2023). "Two components of MoRAL scores, AFP and PIVKA, are associated with aggressive tumor behaviors and poor clinical outcomes." (PMID 36925930, 2023). "The R848@M2pep-MPsAFP-reprogrammed M2-like TAMs not only relieved tumor immunosuppressive microenvironment, but also functioned as APCs to present AFP antigen with the help of the adjuvant R848 to drive CD8+ T cell-mediated antigen-specific antitumor immunity." (PMID 37704614, 2023). "Univariate analysis showed that the tumor number (P<0.001), maximum tumor diameter (P<0.001), AFP level (P<0.001), GLR (P<0.001), and SII (P<0.001) were all significantly associated with RFS among HCC patients." (PMID 37152021, 2023). "Low GADD45G expression was related to high tumor T stage, high pathologic stage, and high AFP levels in patients with HCC." (PMID 37833694, 2023). "After the completion of bridging CDCT, only (61.5%) of the respondents required both tumor markers (AFP, BHCG, LDH) and radiological images." (PMID 37504318, 2023). "For example, SERPINA1 expression was significantly connected to adjacent inflammation, tumor size, pathologic stage, and AFP level in LIHC." (PMID 37511325, 2023). "For example, we included an inoperable HCC patient with a tumor size of 140mm, a positive serum AFP value, and an AJCC stage of T3N0M0." (PMID 36798659, 2023). "On the other hand, according to the results of stratified intergroups, patients with tumours < 5 cm and lower AFP more or less presented superiorities in the LOS, tumour response and AEs." (PMID 36631744, 2023). "FOXM1 expression demonstrated significant correlations with age, tumor stage, tumor grade, vascular invasion, hepatic inflammation, and AFP levels." (PMID 37817774, 2023). "Immunohistologically, the tumor was finally diagnosed as ectopic HCC with alpha-fetoprotein positive expression." (PMID 38156130, 2023). "Intra-hepatic CD68+ TAMs were associated with high HBV-DNA, high tumor differentiation, small tumor size, abnormal AFP and increased tumor number." (PMID 35347503, 2023). "The nomogram illustrated tumor number as sharing the largest contribution to the OS with the regression coefficients of 0.45 in the Cox model, while prior surgery, AFP, PLT, and ALP showed a moderate impact on the OS." (PMID 37287040, 2023).